EGFR (epidermal growth factor receptor)
Diseases named in the same sentence as EGFR in open-access papers (continued):
Sharing a sentence is not in itself a finding about the gene and the disease.
Pleural effusion (110 papers, 2005 to 2026). The presence of an excessive amount of fluid in the pleural cavity. "Critically, dynamic genetic profiling of the pleural effusion in November 2024 identified an emergent EGFR L858R mutation-a finding contrary to the typical mutual exclusivity described in this subgroup and suggests therapy-induced clonal selection." (PMID 41959900, 2026). "In terms of EGFR mutation, vascular convergence sign was significantly more prominent in tumors with this mutation, while pleural effusion, pericardial effusion, pleural thickening, and other signs in tumor imaging were not." (PMID 40075729, 2025). "An EGFR exon 20 T790M mutation was confirmed in pleural effusion and re-biopsy samples, leading to the initiation of the third-generation EGFR-TKI lazertinib." (PMID 38773241, 2024). "There were 6 patients who tested samples from initial biopsy and plasma, 1 from pleural effusion and plasma, 2 from plasma and 2 from initial biopsy, all tested samples had proven the existence of EGFR mutations." (PMID 37436674, 2024). "Another mutational alteration found in our series was the EGFR-L858R mutation in a patient with pleural effusion." (PMID 37371673, 2023). "In Patient 12, who carried an EGFR ΔE746-A750 mutation, intrapleural administration of arsenic reduced the volume of the pleural effusion and the number of tumor cells in the pleural effusion." (PMID 37371816, 2023). "In Patient 10 with EGFR T790M mutation, the color of the pleural effusion changed from dark red to light red with a decrease in the number of tumor cells." (PMID 37371816, 2023). "By multivariate cox regression analysis, PFS in overall patients with NSCLC was significantly associated with EML, EGFR mutation, performance status, and pleural effusion." (PMID 35948652, 2022). "Regarding prognostic factors associated with 1-year PFS and OS in patients with NSCLC; ECOG PS, EGFR mutation, pleural effusion, and EML were associated with 1-year PFS and OS, except for 1-year OS for EML." (PMID 35948652, 2022). "detected EGFR mutations in 11 of 43 supernatants from pleural effusion samples through direct sequencing." (PMID 35141163, 2022). "Among them, sixty (90.0%) patients were identified with EGFR T790M mutation, with 22/23 (95.7%) pleural effusion were T790M+, and 38/42 (88.4%) tissue were T790M+." (PMID 35643428, 2022). "ECOG PS (HR 0.164, 95% CI 0.098–0.275, P < 0.001), EGFR mutation (HR 2.664, 95% CI 1.348–5.262, P = 0.005), pleural effusion (HR 0.497, 95% CI 0.356–0.695, P < 0.001) and EML (HR 0.630, 95% CI 0.441–0.899, P = 0.011) were associated with 1-year PFS." (PMID 35948652, 2022). "Univariate analysis showed that EGFR mutation subtype, control of pleural effusion, first-line treatment agents, and first-line treatment efficacy were significantly associated with PFS (P < 0.05)." (PMID 35340158, 2022). "On the other hand, positive EGFR mutation is a protective factor in OS for malignant patients with pleural effusion (HR 0.65; 95% CI 0.56–0.74)." (PMID 35209915, 2022). "There was no meaningful difference between tumor size, lobulated sign, pleural effusion, pericardial effusion, pleural thickening and EGFR mutation rate." (PMID 36685887, 2022). "One-year OS was associated with ECOG PS (HR 0.181, 95% CI 0.119–0.276, P < 0.001), EGFR mutation (HR 2.171, 95% CI 1.006–4.684, P = 0.048), and pleural effusion (HR 0.634, 95% CI 0.430–0.935, P = 0.021)." (PMID 35948652, 2022). "A total of 34 patients (73.9%) used a blood sample to detect EGFR T790M‐cis‐C797S mutation and 12 patients (26.1%) were detected by tissue sample, including lung tissue, pleural effusion, and ascites." (PMID 34612594, 2021). "According to a meta-analysis of 1226 East Asian NSCLC patients, compared with tumor tissues, the comprehensive sensitivity and specificity of detecting EGFR gene mutation in pleural effusion samples were 0.86 and 0.93, respectively." (PMID 35049681, 2021).
Pleural effusion (continued). "Three activating EGFR gene mutations were detected in the malignant pleural effusion samples (c.2235_49del15, p.E746_A750del5; c.2573T>G, p.L858R and c.2240_2257del18, p.L747_P753delinsS; 3/36, 8.3%) (cases 1–3)." (PMID 34257581, 2021). "Another clinical sample, LC133-O, was established from the thoracoscopic biopsy of a treatment-naive patient harboring the EGFR Del19 mutation with N2 lymph nodes metastases and pleural effusion." (PMID 33972544, 2021). "Among them, 132 patients with relatively complete clinical data and with EGFR gene mutation detection of paraffin-embedded pleural effusion sediment section according to the established quality control standard were included." (PMID 33357312, 2020). "In this study, we focused on patients treated with osimertinib whose mutation status of EGFR T790 M was identified by fluid samples, including pericardial, abdominal and pleural effusion." (PMID 31183631, 2020). "A number of studies have shown that pleural effusions are more sensitive to detecting EGFR mutation status than blood samples." (PMID 31691525, 2020). "SCARNA7, MALAT1, and NONHSAT017369 showed consistent results with plasma in pleural effusions compared to EGFR wild‐type, all upregulated in the EGFR mutation group." (PMID 31691525, 2020). "To improve the specificity and sensitivity of this study, we used Clariom D Human Chip technology to detect pleural effusions with different EGFR mutation status." (PMID 31691525, 2020). "That study found that the results of pleural effusion were 100% matched with tumor tissue, and three patients with positive EGFR mutations were found among 19 EGFR wild‐type patients." (PMID 31691525, 2020). "The aim of this study is to retrospectively analyze the results of EGFR gene mutation in pleural effusion sediment section according to strict pathological quality control standards, and the therapeutic effect of EGFR-TKIs guided by this detection results." (PMID 33357312, 2020). "The amplification‐refractory mutation system method was used to test the EGFR mutation status in tumor tissues and pleural effusions of NSCLC patients." (PMID 31691525, 2020). "In recent years, several studies have shown that the specificity and sensitivity of pleural effusion detection of ctDNA EGFR mutation status are close to, or even higher than, that of tumor tissue." (PMID 31691525, 2020). "The 19-Del mutation was found in the exon for the epidermal growth factor receptor gene in the pleural effusion of a patient on March 11th, 2015." (PMID 30851728, 2019). "Clinical factors such as age, gender, histology, pleural effusion and gene mutations with epidermal growth factor receptor/anaplastic lymphoma kinase/ROS proto-oncogene 1 receptor tyrosine kinase (EGFR/ALK/ROS1) were analyzed." (PMID 30909993, 2019). "When using EV-derived DNA from the supernatant of the pleural effusions for EGFR genotyping, two more T790 M mutations were detected in comparison with using cfDNA from the supernatant of the pleural effusions." (PMID 30526536, 2018). "Liquid biopsy using cfDNA from pleural effusion supernatants missed two cases of tissue-based EGFR mutations and found two additional EGFR mutation cases." (PMID 30526536, 2018). "We observed that EGFR genotyping using cfDNA from the supernatant of pleural effusions missed two tissue-proven EGFR mutations but detected two more mutant cases in patients diagnosed as tissue wild-type." (PMID 30526536, 2018). "Other novel resistance mechanisms to third-generation EGFR inhibitors such EGFR C797G mutation and EGFR L798I mutation have also been identified by NGS of pleural effusion and ctDNA, respectively." (PMID 29061113, 2017). "From January 2011 to June 2015, there were 160 molecular tests done for pleural effusion; 101 were positive for EGFR mutations (63%)." (PMID 27352172, 2016). "The pleural effusion with the EGFR mutation showed a dose-dependent growth reduction upon treatment with erlotinib." (PMID 27548442, 2016).
Pleural effusion (continued). "A few reports reported that compared with tumor tissue, pleural effusion cell block had 81.8% sensitivity and 80% specificity for detection of EGFR mutation and 62.5% to 100% sensitivity and 100% specificity for ALK detection." (PMID 27880851, 2016). "At the time of disease progression to chemotherapy, a recheck of EGFR mutation status over right pleural effusion still yielded T790M mutation, despite a long EGFR-TKI-free period (409 days) and an experience of objective response to chemotherapy." (PMID 27384480, 2016). "Nineteen samples were contributive, 16 were EGFR mutated and 3 were wild type: 1 pleural effusion, 1 bronchial aspirate and 1 bronchial biopsy with 5, 5 and 10% tumor cell content respectively." (PMID 24885034, 2014). "In the second case, progression was seen 11 months after local therapy with a pleural effusion, proven to be adenocarcinoma with EGFR mutation." (PMID 25538894, 2014). "The detection of EGFR mutation needs surgical specimen, bronchoscopic or CT-guided needle biopsy tissue, bronchial lavage fluid and pleural effusion with tumor cell." (PMID 25490772, 2014). "In that study, at least 2 out of 11 patients with activating EGFR mutations who had become refractory to gefitinib treatment displayed EGFR mutation loss at recurrence in disseminated cancer cells from pleural effusions." (PMID 24643470, 2014). "Although the more common presentation of pleural metastases in patients with EGFR mutations was suggested in other genetic studies regarding pleural effusion, we observed an interesting finding of the predominant presentation of PMME in EGFR-mutant tumors." (PMID 22091430, 2011). "In this study, we assessed the feasibility of detection of EGFR mutations in samples of pleural effusion fluid." (PMID 17060940, 2006). "Because of its high sensitivity and specificity, PNA-LNA PCR clamp was considered suitable to detect EGFR mutations both in histological samples such as surgical specimens, and in cytological samples such as sputum and pleural effusions." (PMID 17106442, 2006). "EGFR mutation status was confirmed by molecular pathology, with tumor biopsy tissue samples used in 35 (81.4%) patients, blood samples in 6 (14.0%) patients and pleural effusions samples in 2 (4.7%) patients." (PMID 36910673, 2023). "In addition, studies reported that the sensitivity of detecting EGFR mutations in the supernatant of pleural effusion were relatively independent from detectable malignant cells and blood cell contamination in pleural effusions." (PMID 33656807, 2021). "The overall concordance rate of EGFR mutation between two kinds of samples was 86.98%, indicating that pleural effusion may be an effective method to screen EGFR mutation for NSCLC patients in advanced stages." (PMID 35049681, 2021). "Previous studies showed that pleural effusion supernatants contain more abundant tumor derived DNA (ctDNA) than pleural effusion sediments and plasma samples, and had higher detection rate of EGFR driver mutations especially for detection of T790M in EGFR‐TKI relapsed patients." (PMID 33656807, 2021). "Clinical characteristics of patients (gender, smoking status, bone metastasis, central nervous system metastasis, pleural effusion, liver metastasis, number of metastatic sites, and type of EGFR mutation) were subsequently correlated with basal values of miR-21, miR-27a and miR-181a." (PMID 34208765, 2021).
Pleural effusion (continued). "Therefore, it is very important to propose quality control standards and guide the detection of EGFR mutation in pleural effusion." (PMID 33357312, 2020). "Finally, a 19-Del mutation in the exon of the EGFR gene was found in gene detection of a patient’s pleural effusion on March 11, 2015." (PMID 30851728, 2019). "Recent studies have shown that the cell-free supernatant of pleural effusion might be a better resource for mutation detection than cell pellets, and EGFR mutations have been identified in supernatant samples." (PMID 30526536, 2018). "We also compared the translational value of the cfDNA and EV-derived DNA extracted from the supernatant of pleural effusions for EGFR genotyping in EGFR-TKI-naïve patients and for detecting the T790 M mutation in patients with acquired resistance to EGFR-TKIs." (PMID 30526536, 2018). "The accompanied high incidence of pleural effusion might cause more compressive atelectasis (nM = 12 vs. nWT = 6) in ADC with EGFR mutation." (PMID 28949965, 2017). "Thirdly, most of the patients had their EGFR T790M mutation diagnosed by using pleural effusion, which might be inconsistent with findings from the tumor tissues." (PMID 28977977, 2017). "Interestingly, a high detection rate of EGFR mutations (approximately 70%) has been reported in malignant pleural effusions of pulmonary adenocarcinoma." (PMID 22091430, 2011). "The results in that patient encouraged us to hypothesise that the EGFR mutation status determined in pleural effusion fluid is useful for predicting the responsiveness to EGFR tyrosine kinase inhibitors." (PMID 17060940, 2006). "However, EGFR mutation subtypes and T790M mutation status may make a difference in the effect of osimertinib on pleural effusion." (PMID 38226415, 2024). "Although more EGFR T790M resistance mutations could be detected in the supernatant of pleural effusion specimens with malignant cells observed, suggesting that analysis may be necessary in combination with cytological evaluation for driver gene testing in patients relapsed from prior TKI treatment." (PMID 33656807, 2021). "EGFR mutations were determined by gene panel sequencing or polymerase chain reaction (PCR)-based assays on different samples (37 from tumor tissue, 24 from CSF, 9 from both CSF and serum, 6 from serum, 3 from both tumor tissue and serum, and 1 from pleural effusion)." (PMID 32736566, 2020). "Because of positive pleural effusion cytology, which was proven after surgery, the patient was diagnosed with pathological Stage IVA with EGFR L858R mutation." (PMID 38962043, 2024). "Cases #224 and #240: both patients demonstrated disease progression accompanied by pleural effusion after receiving third-generation EGFR-TKI osimertinib." (PMID 38773241, 2024). "Patient 5 with the EGFR L858R mutation underwent an intrapleural administration of ATO, and pleural effusions were collected for 4 consecutive days after the administration." (PMID 37371816, 2023). "Here, we found that arsenic decreased the number of clusters of tumors cells isolated from pleural effusions in NSCLC patients with different EGFR genotypes." (PMID 37371816, 2023). "In a study involving 192 NSCLC patients in the advanced stage, 119 (61.98%) matched primary tumor tissues were EGFR mutant, and so were 113 (58.85%) pleural effusion samples." (PMID 35049681, 2021). "NCCLu-045 and 049 were derived from the pleural effusion of a patient with resistance to first-generation EGFR TKI (gefitinib) who received multiple chemotherapies; however, its growth pattern was different in suspended or adherent cultures, respectively." (PMID 34830169, 2021). "He eventually developed excess pleural effusion and liquid biopsy molecular testing revealed an EGFR T790M resistance alteration." (PMID 32560187, 2020). "EGFR mutations were detected by Amplification Refractory Mutation System (ARMS) and ABI 7500 Fluorescence quantitative PCR with pleural effusions." (PMID 32127953, 2020).
Pleural effusion (continued). "Five lncRNAs significantly associated with EGFR mutation status were screened by FC value and GO analysis, and then evaluated by real‐time quantitative polymerase chain reaction in NSCLC patients' pleural effusions." (PMID 31691525, 2020). "Out of 32 EGFR TKI-naive patients, with known EGFR tissue genotype, EV EGFR genotyping in pleural effusions correctly identified 19 EGFR mutant cases." (PMID 33143170, 2020). "Eighty-three patients underwent semirigid pleuroscope for workup of an undiagnosed pleural effusion, and 9 patients with EGFR mutation NSCLC and clinical resistance to an EGFR TKI underwent repeat biopsy for tumor genotyping by semirigid pleuroscope." (PMID 29610630, 2018). "On this basis, we investigated the feasibility of EGFR genotyping using the supernatant of pleural effusions in comparison with tissue-based genotyping in patients with pulmonary adenocarcinoma." (PMID 30526536, 2018). "In conclusion, the supernatant of pleural effusions is particularly more effective for EGFR genotyping than conventional cytology or cell block samples for patients with pulmonary adenocarcinoma." (PMID 30526536, 2018). "Here, we investigate the efficiency of liquid biopsy using cell-free DNA (cfDNA) and extracellular vesicle-derived DNA (EV-derived DNA) from the supernatant of pleural effusions for EGFR genotyping in patients with pulmonary adenocarcinoma." (PMID 30526536, 2018). "Third, EV-derived DNA from the supernatant of pleural effusions outperformed cfDNA from pleural effusions for the EGFR genotyping of patients with pulmonary adenocarcinoma with pleural effusion." (PMID 30526536, 2018). "After centrifuging pleural effusion, the pleural effusion pellet was sent to clinical laboratory and subject to immunohistochemical staining against EGFR." (PMID 30425968, 2018). "EGFR genotyping in pulmonary adenocarcinoma patients who develop pleural effusions is mostly performed using cytology or cell block slides with low sensitivity." (PMID 30526536, 2018). "Liquid biopsy using the supernatant of pleural effusions showed significantly improved results for EGFR genotyping compared to those using conventional cell block or cytology samples." (PMID 30526536, 2018). "EGFR genotyping using EV-derived DNA from the supernatant of the pleural effusions detected T790 M in 13 of the 18 (72%) patients (nine patients with T790 M + Exon 19 del and four patients with T790 M + L858R)." (PMID 30526536, 2018). "EV-derived DNA from the supernatant of pleural effusions is promising for EGFR genotyping including T790 M detection in pulmonary adenocarcinoma patients who develop pleural effusion." (PMID 30526536, 2018). "EGFR genotyping using cfDNA from the supernatant of the pleural effusions found T790 M in 11 of 18 (61%) patients (seven patients with T790 M + Exon 19del and four patients with T790 M + L858R)." (PMID 30526536, 2018). "In this study of pulmonary adenocarcinoma patients with pleural effusions that developed before or after EGFR-TKI treatment, we identified several interesting findings." (PMID 30526536, 2018). "Liquid biopsy using EV-derived DNA is promising for EGFR genotyping, including T790 M detection in pulmonary adenocarcinoma patients who develop pleural effusions." (PMID 30526536, 2018). "EV-derived DNA and cfDNA were extracted from the supernatant of pleural effusions from patients who were EGFR-TKI naïve (case 9)." (PMID 30526536, 2018). "Compared with tissue EGFR genotyping for EGFR mutant cases, EGFR genotyping using cfDNA from the supernatant of pleural effusion detected 17 of the 19 (89%) mutant cases." (PMID 30526536, 2018). "Tumor tissue specimens were obtained at secondary biopsy from 18 patients and malignant fluid (pleural effusion or ascites) was collected from 23 patients after the development of acquired resistance to EGFR-TKIs." (PMID 27542267, 2016).